WASH3P (WASP family homolog 3, pseudogene)
Description:
Acts as a nucleation-promoting factor at the surface of endosomes, where it recruits and activates the Arp2/3 complex to induce actin polymerization, playing a key role in the fission of tubules that serve as transport intermediates during endosome sorting. Involved in endocytic trafficking of EGF. Involved in transferrin receptor recycling. Regulates the trafficking of endosomal alpha5beta1 integrin to the plasma membrane and involved in invasive cell migration (By similarity). In T-cells involved in endosome-to-membrane recycling of receptors including T-cell receptor (TCR), CD28 and ITGAL; proposed to be implicated in T cell proliferation and effector function. In dendritic cells involved in endosome-to-membrane recycling of major histocompatibility complex (MHC) class II probably involving retromer and subsequently allowing antigen sampling, loading and presentation during T-cell activation. Involved in Arp2/3 complex-dependent actin assembly driving Salmonella typhimurium invasion independent of ruffling (By similarity). Involved in the exocytosis of MMP14 leading to matrix remodeling during invasive migration and implicating late endosome-to-plasma membrane tubular connections and cooperation with the exocyst complex (By similarity). Involved in negative regulation of autophagy independently from its role in endosomal sorting by inhibiting BECN1 ubiquitination to inactivate PIK3C3/Vps34 activity (By similarity).
Synonyms: FLJ25222; formerly FAM39DP
Gene: Transcribed unprocessed pseudogene on chromosome 15 (101,966,075 to 101,976,266, forward strand). Ensembl gene ENSG00000185596.
Subcellular location: Early endosome; Early endosome membrane; Recycling endosome membrane; Cell projection, lamellipodium; Cell projection, filopodium; Cytoplasmic vesicle, autophagosome; Cytoplasm, cytoskeleton, microtubule organizing center, centrosome, centriole
Diseases named in the same sentence as WASH3P in open-access papers:
WASH3P is named in the same sentence as 2 diseases in open-access papers, as found by Europe PMC text mining. Sharing a sentence is not in itself a finding about the gene and the disease. The quoted sentences say what the papers report.
renal cell carcinoma (1 paper, 2016). "In addition, a link between WASH3P and cancer is supported by our findings; since mutations in a region indicate involvement in NSCLC and renal cell carcinoma." (PMID 27150584, 2016).
WASH3P also shares sentences with these, for which no sentence is quoted: cancer (1 paper).